IL1B (interleukin 1 beta)
Diseases named in the same sentence as IL1B in open-access papers (continued):
Sharing a sentence is not in itself a finding about the gene and the disease.
Hyperglycemia (325 papers, 2007 to 2026). An increased concentration of glucose in the blood. "Endothelial activation induced by hyperglycemia and inflammation increased CysLTR1 expression, triggering autophagy within two to six hours, IL-1β production, loss of junction integrity, decreased TER, and increased leukocyte migration within six to 24 hours." (PMID 39504050, 2024). "Using Müller cells known to produce active caspase-1 and IL-1β under hyperglycemic conditions we confirmed that prolonged exposure to hyperglycemia leads to caspase-1/IL-1β/IL-1R1 feedback signaling causing sustained caspase-1 activity." (PMID 39483336, 2024). "Caspase-1 also regulates the expression of key hyperglycemia-induced genes, such as IL-1β, SIRT-1, and NF-Kβ, that have been implicated in diabetes-associated complications." (PMID 37759966, 2023). "In uninjured corneas of wild-type mice, hyperglycemia upregulated the expression of IL-1β, IL-1Ra, and ICAM1, whereas IL-36R deficiency attenuated this increase." (PMID 37371057, 2023). "Molecules involved in the immune system response such as IL-1β, which is elevated due to chronic hyperglycaemia, have also been linked to acceleration of hIAPP aggregation." (PMID 35455074, 2022). "The levels of IL-1β are increased during hyperglycemia, and elevation of IL-1β has been shown to increase the risk of T2D." (PMID 36230963, 2022). "For example, HIF-1α-mediated regulation of the NLRP3/IL-1β signalling pathway has been reported to play a role in susceptibility to pulmonary aspergillosis in a hyperglycaemia mouse model." (PMID 36275017, 2022). "Müller cells are especially involved in DR-associated inflammatory processes, as hyperglycemia induces Müller cells to express a number of pro-inflammatory cytokines, including IL-1β and TNF-α, which together upregulate IL-8." (PMID 35709240, 2022). "To further elucidate the association between hyperglycaemia and H2S biosynthesis in DB-OA cartilage, we performed an in vitro model of glucose-induced stress in IL-1β-activated chondrocytes." (PMID 35453313, 2022). "Diabetic patients manifest inflammatory phenotype possibly due to damage to the beta cells and target receptors of insulin caused by chronic hyperglycemia and Interleukin-1 beta (IL-1β) stress." (PMID 34295586, 2021). "Hyperglycemia causes oxidative stress in these cells, which in turn promotes inflammasome scaffolding, caspase-1 activation, and production of IL-1β." (PMID 34944138, 2021). "Collectively, our data indicate that Qβ-N-term (s-s) is efficient at delaying onset of hyperglycemia, caused by a reduction of amyloidogenic deposits together with a local reduction of the pro-inflammatory cytokine IL-1β." (PMID 32131431, 2020). "Since Interlukin-1 β (IL-1β) has a pivotal role in inflammation, Tg (ins:il1b) zebrafish were used to identify underlying processes leading to β cell dysfunction and its following consequences such as hyperglycemia." (PMID 32765420, 2020). "Instead, salivary gland dysfunction was associated with hyperglycemia and elevation of serum IL1β, IL16, and CXCL13." (PMID 31784615, 2019). "Experimental DM in rodents is associated with β cell apoptosis that leads to hyperglycemia, the macrophage proinflammatory cytokine (IL-1β in combination with IFN-γ and TNF-α), playing an essential role in β cell dysfunction and death." (PMID 30818888, 2019). "In this study, we examined the underlying mechanisms of secreting IL-1β during hyperglycemia, with a focus on the alteration of Ca2+ homeostasis and lysosomal exocytosis." (PMID 28970837, 2017). "The association of IL-1β release by astrocytes and microglia prompts the investigation of how exactly is hyperglycemia mediating such effects." (PMID 26514658, 2015). "HFFD-induced altered lipid profiles and hyperglycemia are closely associated with elevated pro-inflammatory cytokines, as we recorded increased concentrations of IL-1β, IL-6, and TNF-α." (PMID 23690866, 2013).
Hyperglycemia (continued). "Hyperglycemia and hyperlipidemia play their permissive role to trigger the secretion of IL-1β from pancreatic islets and cause dysfunction of β-cells in diabetic GK rats." (PMID 23409091, 2013). "Hyperglycaemia up-regulated the expression of several proinflammatory genes, including those encoding for IL-1β and TNF-αin vitro, the latter gene via increased recruitment of nuclear factor kappa B (NF-κB) p65 to the TNF-α promoter." (PMID 18290856, 2008). "Elevated levels of IL-1β in gingival crevicular fluid and saliva are strongly associated with increased periodontal disease severity, particularly in diabetic individuals, where hyperglycemia further enhances its production, prolonging inflammatory activity." (PMID 40283677, 2025). "Maternal hyperglycemia associated with urinary incontinence creates an inflammatory environment, characterized by reduced melatonin and IL-10 and increased IL-1β, IL-8, and TNF-α in the plasma of mothers with gestational diabetes mellitus and incontinence-specific urinary tract issues." (PMID 41295285, 2025). "In addition, berberine can inhibit the activation of NF-κB caused by hyperglycemia and the increase of pro-inflammatory factors and chemokines such as TNFα, IL1-β, IL8 and MCP1." (PMID 37780378, 2023). "Hyperglycemia can cause chronic inflammation, promote infiltration of inflammatory cells in renal tissues, and produce large amounts of proinflammatory factors, such as IL-1β, IL-6, and TNF-α." (PMID 36425593, 2022). "In the present study, IL-1β and TGFβ expression increased in the ileum, indicating that the regulation of IL-1β and TGFβ is associated with the effect of statins on the alleviation of hyperglycemia, hyperlipidemia, and inflammation." (PMID 31551944, 2019). "The higher production of IL-1β in diabetic mice suggests that this cytokine is an important marker of severity of PD, which in presence of hyperglycemia induces activation of ACEs, causing local immune dysfunction and cytokine imbalance promoting elevation of IL-1β." (PMID 31333451, 2019). "Previous studies have suggested that hyperglycemia may cause ICAM-1 increases through the activation of IL-1β and the p38 MAPK pathway." (PMID 25389378, 2014). "Hyperglycaemia is known to cause immune dysfunction, adversely affecting leukocyte function and leading to the increased production and secretion of cytokines, such as IL-6, IL-1β and TNF-α, leaving diabetic patients more susceptible to infections and related comorbidities." (PMID 37627482, 2023). "Maternal hyperglycemia during pregnancy decreased IL-1β, increased TNF-α, and the receptor for advanced glycation end-products in the offspring hippocampus." (PMID 41590515, 2026). "Chronic unpredictable mild stress induced hyperglycemia, increased erythrocyte hemolysis, hepatic vacuolation, renal tubular injury, and upregulation of pro-inflammatory cytokines (IL-1β and TGF-β1) in the ileum, caecum, and hypothalamus." (PMID 41300053, 2025). "In vitro experiments revealed that Cur effectively mitigated hyperglycemia/IL-1β (HG/IL-1β)-induced HUVECs senescence through NRF2/HO-1 pathway activation." (PMID 40688662, 2025). "The results showed that in rats with hyperglycemia, the concentrations of pro-inflammatory factors NF-κB p-p65 and IL-1β increased significantly, whereas the anti-inflammatory factor IL-10 decreased significantly." (PMID 41463431, 2025). "In T2D, IL-1β expression is upregulated by hyperglycemia through NF-κB pathway activation, resulting in β-cell apoptosis and impaired insulin secretion." (PMID 40804870, 2025). "Hyperglycemia increases the production of proinflammatory mediators, such as IL-6, IL-1β, and TNF-α, which play a crucial role in the development of chronic inflammation and thus impair immune system function." (PMID 41009326, 2025). "During hyperglycemia, the overproduction of reactive oxygen species (ROS) triggers the release of pro-inflammatory cytokines such as IL-6, IL-1β, TNF-alpha, and IFN-γ." (PMID 39940428, 2025).
Hyperglycemia (continued). "Traumatic injury triggers substantial release of pro-inflammatory cytokines (IL-6, TNF-α, IL-1β) that induce stress hyperglycemia, which subsequently enhances neuronal excitability through glutamate-mediated mechanisms." (PMID 40303892, 2025). "Meanwhile, silencing AQP4‐AS1 can downregulate the expression levels of VEGF, IL‐6, IL‐1β, and Intercellular Adhesion Molecule‐1, and reduce hyperglycemia‐induced retinal inflammasome." (PMID 41497475, 2025). "Prolonged exposure to stress-related factors, including excessive β-cell stress, free radicals, hyperglycemia, and IL-1β produced by host pancreatic immune cells, results in increased expression of Fas on the surface of β-cells." (PMID 41185072, 2025). "IL1β expression is increased in sand rat islets due, at least partly, to hyperglycemia as treatment with phlorizin, a drug reducing blood glucose levels by inhibiting glucose absorption in the gut, reduces IL1β expression in the islets." (PMID 38540087, 2024). "A similar hyperglycemia-mediated caspase-1/IL-1β/IL-1R1 feedback signaling was detected in vitro in human Müller cells which was prevented by treatment with IL-1ra." (PMID 39483336, 2024). "To further establish a hyperglycemia-induced caspase-1/IL-1β/IL-1R1 feedback loop we used isolated human Müller cells (hMC)." (PMID 39483336, 2024). "We were able to show that hyperglycemia initiates caspase-1 activity and IL-1β continues to promote caspase-1 activation." (PMID 39483336, 2024). "Inhibition of IL-1β has been shown to reduce hyperglycemia and inflammation in obese mice and diabetic rats." (PMID 38257186, 2024). "Previously we have shown that hyperglycemia induces caspase-1 activation and IL-1β production in hMCs." (PMID 39483336, 2024). "This current study demonstrates that hyperglycemia-induced Müller cell death fulfills all criteria for pyroptosis and links the pro-inflammatory function of caspase-1 and IL-1β production to cell death." (PMID 39483336, 2024). "Studying hMGECs exposed to hyperglycemia or IL-1β would offer a better insight into the impact of metformin on the meibomian glands of diabetics." (PMID 39768389, 2024). "Treatment of hMCs with IL-1β in 5 mmol/L glucose media led to a 2.38 ± 0.6 fold increase in RIP2 protein levels demonstrating that both stimuli, hyperglycemia and IL-1β, upregulate the expression of RIP2." (PMID 39483336, 2024). "Inflammatory factors, such as IL-6, TNF-α, cleaved caspase-1, and pro-IL-1β are downstream of the NF-κB signaling pathway and are also involved in neuroinflammation induced by hyperglycemia." (PMID 38421831, 2024). "RIP2 is not only involved in hyperglycemia-induced caspase-1 activation but also promotes caspase-1 activation by IL-1β." (PMID 39483336, 2024). "As in hMG, hRMEC were cultured for 24 h in media supplemented with elevated glucose for hyperglycemia, palmitic acid for dyslipidemia, and IL-1β for chronic inflammation." (PMID 39716241, 2024). "A prospective cohort study that follows up patients with TB and hyperglycemia in the course of disease and treatment is essential to define the factors behind varying patterns of IL-1β levels among patients with DM-TB." (PMID 39981106, 2024). "The largest decrease for IL-1β, IL-6, and IL-8 was observed in normoglycemia-simulating conditions compared to both hypo- and hyperglycemia (p < 0.05)." (PMID 38542084, 2024). "(Poly)phenol metabolites quantified in lipoproteins were evaluated towards the inflammatory response of endothelial HMEC-1 cells exposed to hyperglycemia by measuring the release of IL-6 and IL-1β into the cell medium after treatment." (PMID 36516720, 2023). "The secretion of the IL-1β cytokine against the effect of hyperglycemia concomitant with the stimulation by LPS+Nigericin was also evaluated." (PMID 37122742, 2023).
Hyperglycemia (continued). "Blockade of NLRP3 inflammasome–mediated secretion of IL-1β in TET2-deficient immune cells using MCC950 suppressed the higher levels of IL-1β and increased hyperglycemia and IR in mice carrying TET2-deficient HSCs." (PMID 37071471, 2023). "AuNPs partially recuperated the antioxidant defense, particularly catalase activity, and inhibited the IL1β proinflammatory cytokine release induced by hyperglycemia." (PMID 37627484, 2023). "In hyperglycemia condition, the excessive production of ROS lead to the release of pro-inflammatory cytokines such as IL-6, IL-1β, TNF alpha, and INFy." (PMID 37175192, 2023). "In cultured macrophages, intermittent episodes of hypoglycemia and hyperglycemia promote M1 polarization and enhance IL-1β, TNF-α, IL-6, and MCP-1 secretion." (PMID 37893217, 2023). "Upregulated level of IL-1β has been reported to be induced by hyperglycemia in human aortic endothelial cells, myocardium, macrophages and hearts from diabetic rats." (PMID 37025617, 2023). "Our study demonstrates that hyperglycemia promotes IL-1β production and pyroptosis in macrophages suffered by periodontal microbial stimuli." (PMID 37047282, 2023). "Previous study has also proved that ALPK1 enhanced production of IL-1β in the kidney of experimental models of hyperglycemia and resulted in the induction of fibrotic renal injury." (PMID 36732854, 2023). "The decreased secretion of anti-inflammatory adiponectin and the increased secretion of pro-inflammatory leptin and IL-6 is reported in GDM, similar to high concentrations of TNF-α and IL-1β due to hyperglycaemia." (PMID 37627482, 2023). "The expression of IL-1β is known to be upregulated in T2DM as a marker of hyperglycemia-induced inflammation, which leads to substantial damage to endothelial cells, thereby contributing to vascular complications in T2DM." (PMID 37759966, 2023). "The byproducts of hyperglycaemia, AGEs, regulate inflammation by increasing NF-κB nuclear localisation and induction of IL-1β, TNF-α, macrophage inflammatory protein 2 (MIP2), IL-6 and IL-10." (PMID 37670018, 2023). "The primary goal of this study was to evaluate the effects of chronic hyperglycemia and immediate insulin treatment on the proportion of IL1β-immunoreactive (IR) myenteric neurons along the duodenum–ileum–colon axis." (PMID 36982878, 2023). "Uric acid significantly increased the expression of IL-6, IL-8 and IL-1β mRNAs when compared with hyperglycaemia alone, which itself induced a significant pro-inflammatory response." (PMID 35503137, 2022). "Excessive ROS produced during hyperglycemia stimulates vascular cells to secrete IL-1β, which disrupt tight junctions, increase permeability, and allow vascular permeability leaking fluids and molecules into the inner membrane, such as ox-LDL." (PMID 35844498, 2022). "We found that hyperglycemia increased the secretion of both IL-1β and its natural inhibitor IL-1RA, confirming our previous data." (PMID 35163309, 2022). "Overall, the strongest enhancing effect of hyperglycemia was detected for IL-1β release 24 h after M(IFNγ) was stimulated with 1 μg/mL Hb-Hp1-1 complexes (6.75 times)." (PMID 35163309, 2022). "Hyperglycemia elicited a strong enhancement of IL-1β release after stimulation with Hb-Hp complexes regardless of the Hp variant, with the strongest effect being detected 24 h after stimulation with 1 μg/mL Hb-Hp1-1 complexes (6.75 times)." (PMID 35163309, 2022). "In this work, we used homozygous, leptin-resistant diabetic db/db mice that are characterized by hypogonadism, hyperglycemia, and testicular inflammation with increased IL-1β and chemokine (C–C motif) ligand 2 (CCL2)." (PMID 35307018, 2022). "Although the mechanisms leading to increased proinflammatory activation are incompletely understood, hyperglycemia has been shown to increase IL-1β expression in different cell types, including adipocytes and adipose tissue." (PMID 36014927, 2022).
Hyperglycemia (continued). "None of the SGLT-2i tested was able to hamper the increase in the mRNA expression of IL-6, IL-8 and IL-1β induced by LPS in THP-1 or by hyperglycaemia in HUVEC, suggesting that these drugs do not have intrinsic anti-inflammatory properties in these settings." (PMID 35503137, 2022). "Hyperglycemia and circulating leptin trigger further production of pro-inflammatory cytokines, such as IL-1β, within the islet." (PMID 35145521, 2022). "We have found that hyperglycemia, via a synergistic interplay of inflammatory (IL-1β) and proliferative stimuli (PDGF-BB), alters lipid metabolism and stimulates mesangial proliferation and release of PGs and LPAs via the cPLA2-COX2 pathway." (PMID 35513427, 2022). "Under hyperglycemia, the production of IL-1β, IL-6, and TNF-α is promoted, thereby accelerating the apoptosis of islet β cells and inducing islet failure." (PMID 35845591, 2022). "Studies demonstrated that kaempferol plays vital nephroprotective roles associating with inhibiting oxidative stress, proinflammatory cytokines (TNF-α and IL-1β), and fibrosis in DN via inhibiting hyperglycemia-induced activation RhoA/Rho-kinase." (PMID 34349833, 2021). "A high blood glucose or a hyperglycemia condition has been considered to trigger oxidative stress and also increase proinflammatory cytokines, such as IL-1β and TNF-α." (PMID 33996978, 2021). "Compared to sustained hyperglycemia, glycemic fluctuation led to further increase in IL-1β, TNFα, RANKL, TLR2/4, IRAK1, and TRAF6 mRNA expression in peri-implant gingival tissues." (PMID 34401982, 2021). "Myricitrin can repair abnormal expression of mRNA IL1β, STAT1b and IκBα in diabetes disorder, thus mainly interfered with toll-like receptor pathway to promote glucose uptake and relieve hyperglycemia level in vivo." (PMID 34358088, 2021). "Postprandial hyperglycemia observed after carbohydrate intake induces pro-inflammatory cytokine expression, including interleukin 1 beta (Il1b) and tumor necrosis factor-α (Tnfa) in peripheral leukocytes." (PMID 34336926, 2021). "Aside from β cells, hyperglycemia is also reported to increase IL-1β generation in adipose tissue and a cardiomyocyte cell lines." (PMID 33546399, 2021). "The upregulation of VCAM-1 by hyperglycemia in endothelial cells also depends on the presence of IL-1β." (PMID 40477401, 2021). "IL-1β levels are elevated in chronic pain and induce hyperglycemia by stimulating the glucocorticoid system and the stress axis." (PMID 34068151, 2021). "Apart from its role in inflammation, IL-1β appears to be connected to hyperglycemia by acting upon the spinal cord, upon the sympathetic nervous system, and upon hypothalamus." (PMID 34068151, 2021). "Proinflammatory cytokines IL-1β, IL-6, IL-18, and TNFα which play major roles in the development and progression of DN are triggered by hyperglycemia and oxidative stress." (PMID 33562428, 2021). "Accordingly, pharmacological blockade of IL-1β in patients with type 2 DM improved beta-cell secretory function and reduced hyperglycemia and markers of systemic inflammation." (PMID 33287713, 2020). "IL-1β also links hyperglycemia to β-cell apoptosis by increasing β-cell expression of the FAS receptor in response to high glucose conditions, which promotes the extrinsic apoptotic pathway when stimulated." (PMID 33457426, 2020). "Both persistent and postprandial hyperglycemia have induced the expression of the IL-1β gene in rats, as evidenced by increased levels of IL-1β protein and mRNA in peripheral blood monocytes." (PMID 32561825, 2020). "During the progression of T2DM, hyperglycemia can not only activate NLRP3 inflammasomes in pancreatic β-cells but also transform pro-IL-1β into biologically active IL-1β." (PMID 33424779, 2020). "In contrast, accumulating data has highlighted the importance and regulation of NLRP3 inflammasome activation and subsequent IL-1β secretion in hyperglycemia." (PMID 31938471, 2020).